BSG (basigin (Ok blood group))
Diseases named in the same sentence as BSG in open-access papers (continued):
Sharing a sentence is not in itself a finding about the gene and the disease.
lung carcinoma (57 papers, 2010 to 2025). "This suggests a possible correlation between the BSG expression and the susceptibility of lung cancer patients to SARS-CoV-2 infection." (PMID 38617561, 2024). "Collectively, our TCGA data analysis validated a significant association between PPIA/BSG overexpression and poor prognoses, such as low survival rate and high cancer stage, in several tumor types, including liver and lung cancers." (PMID 36012604, 2022). "Then we compared the ACE2 mRNA and BSG mRNA expression in normal lung tissues and lung cancer tissues based on 994 samples from TCGA dataset." (PMID 38484369, 2024). "Compared to normal human lung epithelial cell line (BEAS-2B), BSG was upregulated in most lung cancer cell lines (H1299, PC-9, A-549)." (PMID 38484369, 2024). "To further explore the protein expression of BSG in lung cancer tissues, we achieved immunohistochemical data from the HPA database." (PMID 38484369, 2024). "Surprisingly, BSG expression was significantly lower in DM and lung cancer patients compared to controls (4th column)." (PMID 38034398, 2023). "Notably, the proteolytic cleavage of BSG by the sheddase TMPRSS11B was shown to enforce lactate export by SLC16A3 in lung cancer." (PMID 40508207, 2025). "And we found BSG was upregulated in most lung cancer cell lines (H1299, PC-9, A549)." (PMID 38484369, 2024). "We then used real-time PCR to validate the expression of BSG in lung cancer tissues and cell lines." (PMID 38484369, 2024). "The results showed that BSG was highly expressed in lung cancer tissue." (PMID 38484369, 2024). "Thus, BSG has the potential to be served as an exciting target for cancer therapy, especially for lung cancer." (PMID 38484369, 2024). "Furthermore, we noticed that the expression of BSG is low in DM and lung cancer patients, in contrast to ACE2." (PMID 38034398, 2023). "Therefore, the present work is an attempt to provide new data supporting the exploitation of MCTs/BSG as targets in lung cancer therapy." (PMID 25894929, 2015). "First, we analysed the expression of MCTs and BSG in a series of human lung cancer tissues." (PMID 25894929, 2015). "Moreover, BSG at mRNA expression level was remarkably higher than ACE2 in normal lung tissues and lung cancer tissues, BSG might be essential for the invasion of SARS-CoV-2 in normal individuals and cancer patients." (PMID 38484369, 2024). "However, the role of MCTs/BSG in lung cancer is controversial and poorly elucidated." (PMID 25894929, 2015). "What is more, BSG at mRNA expression level was 319.8 folds higher than ACE2 in normal lung tissues, and 151.1 folds in lung cancer tissues." (PMID 38484369, 2024). "In lung cancer patients, the average expression of AXL, BSG, KEEMEN1, and TFRC was very low compared to controls." (PMID 38034398, 2023). "To validate the key role of these transporters in lung cancer, we first analysed the expression of MCT1/4 and BSG in 50 non-small lung cancer (NSCLC) cases." (PMID 25894929, 2015). "Moreover, BSG at mRNA expression level was higher than ACE2 in normal lung tissues, and lung cancer tissues." (PMID 38484369, 2024). "However, the expressions of other receptors (AXL, BSG, KREMEN1, and TFRC) were significantly down-regulated in lung cancer patients." (PMID 38034398, 2023). "Notably, the expression levels of both PPIA and BSG were increased at advanced cancer stages in liver hepatocellular carcinoma and lung adenocarcinoma, indicating that the overexpression of CypA/CD147 may be associated with the poor prognosis of patients with liver or lung cancer." (PMID 36012604, 2022). "In this study we first observed that MCT1, MCT4 and BSG were overexpressed in human lung cancers when compared to adjacent non-tumour tissue." (PMID 25894929, 2015).
ovarian carcinoma (52 papers, 2006 to 2026). A malignant neoplasm originating from the surface ovarian epithelium. "High expression of BSG/CD147 is a marker of poor prognosis in head and neck squamous cell carcinoma, breast and ovarian cancer." (PMID 38398114, 2024).
viral infection (51 papers, 2017 to 2026). "The transmembrane glycoprotein basigin (BSG) or cluster of differentiation 147 (CD147), known to mediate bacterial and viral infections, has been implicated in the viral entry of SARS-CoV." (PMID 37867557, 2023). "BSG/CD147 has been implicated in tumor metastasis, inflammation and viral infection and also previously shown to facilitate SARS-CoV invasion in host cells." (PMID 35517495, 2022). "BSG is widely expressed in epithelial and immune cells and served a variety of vital functions, including inflammatory, immune responses, tumor progression, bacterial and viral infections." (PMID 38484369, 2024). "In addition, BSG has numerous interacting partners, including cyclophilin A (CyPA), a member of the immunophilin family, is also important in viral infections." (PMID 38484369, 2024). "BSG expression is increased in a range of cardiovascular diseases, which could compensate for any age- or disease-associated reductions in ACE2 in regard to viral infection." (PMID 33073064, 2020). "Using human pluripotent stem cell-derived podocytes, Kalejaiye and colleagues identified not only ACE2 but also BSG/CD147 as mediators of SARS-CoV-2’s entry into these podocytes, and they showed the direct viral infection of these cells in vitro." (PMID 39337465, 2024). "The authors concluded that CD147 downregulation affected viral infection indirectly and not via the CypA-CD147 interaction, since they also observed lower ACE2 levels upon BSG knockdown and both receptors were considerably decreased upon SARS-CoV-2 infection." (PMID 39963132, 2025). "However, unlike ACE2, which directly mediates viral infection, some studies suggest that the binding of BSG to the spike protein may not be directly associated with viral entry into host cells, and its role may be that of serving as an auxiliary binding receptor for the virus." (PMID 38034398, 2023). "However, BSG KO and NPR1 KO kidney organoids clearly supported viral infection as demonstrated by confocal microscopy and TEM analysis, thus excluding an essential role of BSG or NRP1 in renal SARS-CoV-2 infections." (PMID 35561674, 2022). "Further, in viral infection assays with authentic SARS-CoV-2 in lung cell lines, we observed no role of BSG in infection." (PMID 33432067, 2021).
liver cancer (46 papers, 2013 to 2025). An epithelial or non-epithelial malignant neoplasm that arises from the liver. "However, our data provide novel insights by demonstrating that the basigin-2 isoform, encoded by ENST00000353555, is the key contributor to the poor prognosis associated with overall BSG expression in liver cancer." (PMID 38975467, 2024). "This study tried to analyze the expression profile and prognostic significance of BSG transcripts in liver cancer." (PMID 38975467, 2024). "Basigin (BSG; CD147) is a transmembrane glycoprotein with high expression levels in liver cancer cells which promotes proliferation and invasion through increasing the secretion of matrix metalloproteinase (MMP)." (PMID 38705513, 2024). "In this study, we systematically analyzed the expression profile and prognostic significance of different BSG transcript isoforms in liver cancer using data from TCGA and GTEx." (PMID 38975467, 2024). "Future mechanistic studies are warranted to better understand the isoform-specific functions of BSG in liver cancer." (PMID 38975467, 2024). "For example, BSG is a target of the drug [131I]‐Metuximab, which is undergoing clinical trial phase 2 for the treatment of liver cancer." (PMID 39207047, 2024). "This study aimed to comprehensively evaluate the prognostic value of total BSG expression and its specific transcript variants, ENST00000353555 and ENST00000545507, in a large cohort of patients with primary liver cancer." (PMID 39006665, 2024). "Based on IHC staining data of BSG in the HPA, we confirmed upregulated BSG expression at the protein level in liver cancer tissues compared to normal liver tissues." (PMID 38975467, 2024). "By replacing total BSG expression with ENST00000353555 in an established ECM-gene-based prognostic signature in liver cancer, it marginally increased the AUC values for one year from 0.79 to 0.80, and five-year OS from 0.72 to 0.73." (PMID 39006665, 2024). "In this study, we aimed to comprehensively evaluate the prognostic value of total BSG expression and its specific transcript variants, ENST00000353555 and ENST00000545507, in a large cohort of patients with primary liver cancer from The Cancer Genome Atlas (TCGA) database." (PMID 39006665, 2024). "BSG is overexpressed in various cancers, including liver cancer." (PMID 38975467, 2024). "Total BSG transcription is a prognostic biomarker for patients with liver cancer." (PMID 38975467, 2024). "Although previous studies have confirmed that BSG expression is an unfavorable prognostic biomarker in liver cancer, transcript-specific prognosis has not yet been explored." (PMID 39006665, 2024).
prostate carcinoma (38 papers, 2008 to 2025). A carcinoma that arises from epithelial cells of the prostate gland. "A recent study showed a significant correlation between serum levels of ADAM12 and BSG from prostate cancer patients." (PMID 31013576, 2019).
glioma (37 papers, 2013 to 2025). A benign or malignant brain and spinal cord tumor that arises from glial cells (astrocytes, oligodendrocytes, ependymal cells). "Particularly, ECs from glioma exclusively expressed a series of transmembrane transport-associated genes, including SLC2A1, BSG, SLC7A1, and SLC7A5, suggesting that ECs in brain tumors were still involved in retaining the brain-blood barrier." (PMID 39345334, 2024). "Impressively, nano-flow cytometry revealed increased CD44/BSG double-positive EVs in EGFRvIII-overexpressing glioma cells compared with their parental cells, which represents a cellular phenotype with strong co-localization in spike-like invadopodia on the plasma membrane." (PMID 37823055, 2023).
glioblastoma (29 papers, 2013 to 2024). The most malignant astrocytic tumor (WHO grade IV). "ApoD and BSG co-labelling is also observed in U87 glioblastoma cells." (PMID 35460054, 2022). "By contrast, the BSG-null cells, and particularly in the presence of iMCT1, showed a high level of sensitivity to phenformin, which is consistent with ATP crisis or “metabolic catastrophe”, as discussed recently and reported for colon adenocarcinoma and glioblastoma cells." (PMID 25894929, 2015).
colon carcinoma (28 papers, 2012 to 2025). "AQP1, a Colton blood group antigen system gene, was reported to be associated with poor prognosis in colon cancer and lung adenocarcinoma, while seven of the fifteen genes were reported to be prognostic in one tumor type (GCNT2, FUT7, FUT3, FUT2, DARC, CR1 and BSG)." (PMID 35955933, 2022).
bladder cancer (27 papers, 2013 to 2025). "Furthermore, BSG associates with chemotherapy response and survival in bladder cancer." (PMID 31013576, 2019). "The higher the expression of BSG in bladder carcinoma, cervical squamous cell carcinoma, liver hepatocellular carcinoma, lung adenocarcinoma, rectal adenocarcinoma, sarcoma, and skin cutaneous melanoma, the worse the patient survival." (PMID 36012604, 2022). "Similarly, we detected bands of a size corresponding to shed BSG in a Western blot of sera from five bladder cancer patients, which we previously reported exhibit high levels of soluble ADAM12 in the circulation." (PMID 31013576, 2019).
myocardial infarction (22 papers, 2009 to 2024). Gross necrosis of the myocardium, as a result of interruption of the blood supply to the area, as in coronary thrombosis. "It has been reported that BSG is highly expressed in monocytes and LV of patients with myocardial infarction." (PMID 28230811, 2017). "BSG and MMPs are upregulated in monocytes of acute myocardial infarction." (PMID 28230811, 2017). "Also, BSG is highly expressed in left ventricle (LV) of patients with myocardial infarction, inflammatory cardiomyopathy, and dilated cardiomyopathy." (PMID 28230811, 2017).
cervical carcinoma (21 papers, 2014 to 2025). A carcinoma arising from either the exocervical squamous epithelium or the endocervical glandular epithelium. "Our findings were consistent with these previous results, and showed that increased mRNA levels of ARF4 and BSG were abnormally overexpressed in cervical cancer samples and its expression correlated with poorer patient prognosis." (PMID 32151082, 2020). "Furthermore, increased BSG expression correlated significantly with poor survival in patients with cervical cancer." (PMID 32151082, 2020). "The upregulated ligand receptor pairs in the cervical cancer group were SPP1 − CD44, FN1 − SDC4, FN1 − SDC1, FN1 − CD44, CD99 − CD99, and the downregulated ligand receptor pairs were PPIA – BSG, LGALS9 − P4HB, LGALS9 − CD44." (PMID 41384115, 2025). "BSG (also known as CD147 and EMMPRIN) is a glycosylated transmembrane protein that is overexpressed in cervical cancer." (PMID 32151082, 2020).
diabetes (20 papers, 2019 to 2025). "Nonetheless, BSG is up-regulated in a range of diseases, including those comorbidities or morbidities associated with increased risk for severe COVID-19 disease and poorer outcomes including thrombosis, pulmonary hypertension, renal disease, obesity, and diabetes." (PMID 33073064, 2020).
non-small cell lung carcinoma (19 papers, 2015 to 2025). A group of at least three distinct histological types of lung cancer, including non-small cell squamous cell carcinoma, adenocarcinoma, and large cell carcinoma. "Furthermore, the gene BSG, when present in non-small cell lung cancer is associated with increased metastatic potential." (PMID 35774118, 2022). "When expressed in non-small cell lung cancer, BSG plays a role in tumour metastasis and invasion." (PMID 35774118, 2022).
malaria (16 papers, 2013 to 2023). Malaria is a serious and sometimes fatal disease caused by a parasite that commonly infects a certain type of mosquito which feeds on humans. "In this work, we set out to characterize the role of CyRPA and RIPR in P. knowlesi that lacks an RH5 orthologue, and to investigate the use of BSG as a receptor for human erythrocyte invasion in two important human malaria-causing agents, P. knowlesi and P. vivax." (PMID 31185066, 2019). "P. falciparum, the cause of the most severe form of malaria, requires the interaction of a trimeric protein complex RH5-CyRPA-RIPR with the host receptor BSG for successful invasion." (PMID 31185066, 2019). "Associations between different isoforms of BSG with malaria outcomes have not yet been identified however in vitro studies have shown a reduced RH5 interaction with isoform 2 of BSG." (PMID 35108259, 2022). "These genes include inflammatory responding genes, such as NFκB and CXCL1, parasite protein receptors, such as BSG and PROCR, and the genes involving protection against malaria, such as HLA-B and HAVCR1." (PMID 26099491, 2015).
lung adenocarcinoma (15 papers, 2011 to 2024). A carcinoma that arises from the lung and is characterized by the presence of malignant glandular epithelial cells. "The results indicated that BSG was barely stained in lung normal tissue, but medium-stained in lung squamous cell carcinoma tissue and high-stained in lung adenocarcinoma tissue." (PMID 38484369, 2024). "In contrast, BSG expression levels were higher at cancer stages 3 and 4 than at cancer stages 1 and 2 in liver hepatocellular carcinoma, lung adenocarcinoma, and pancreatic adenocarcinoma." (PMID 36012604, 2022). "Interestingly, the expression levels of PPIA and BSG in lung squamous cell carcinoma did not affect patient survival, whereas the overexpression of PPIA and BSG decreased survival of patients with lung adenocarcinoma." (PMID 36012604, 2022). "However, lung adenocarcinoma showed a similar expression pattern of between PPIA and BSG in all cancer stages, indicating that targeting CypA/CD147 interactions may be more effective for the treatment of lung adenocarcinoma than lung squamous cell carcinoma." (PMID 36012604, 2022). "In lung adenocarcinoma, the expression levels of PPIA and BSG gradually increased until cancer stage 3, but there was no further increase in cancer stage 4." (PMID 36012604, 2022).
multiple myeloma (13 papers, 2014 to 2026). "We previously showed that SNPs can act as biomarkers in AML, and we identified some BSG and MCT1 variants that were associated with survival in multiple myeloma patients; most importantly, BSG allele rs4919859 C was associated with worse MM progression-free survival." (PMID 35054026, 2022). "Studies on multiple myeloma (MM) proved that BSG expression is increased and this increase accompanied disease progression." (PMID 35054026, 2022). "BSG was studied in many solid tumours, as well as recently in multiple myeloma and acute lymphoblastic leukaemia." (PMID 35054026, 2022). "BSG is of major importance in myeloma cells, due to its participation in the transport of energy metabolism products, most importantly lactate anions." (PMID 29695106, 2018). "Other studies showed increased lactate export in myeloma cells, and a correlation of BSG gene expression with key regulators of Warburg effect, further confirming the role of BSG in lactate transport in MM." (PMID 29695106, 2018). "Thus, cyclophilin A secreted by endothelial cells in bone marrow blood vessels attracts myeloma cells, which strongly express BSG, the major receptor for cyclophilin A." (PMID 39273126, 2024). "BSG overexpression was shown for many tumours, and has also been proved in multiple myeloma." (PMID 29695106, 2018). "In conclusion, our study shows that selected BSG and SLC16A1 genetic variants may affect progression-free and overall survival in multiple myeloma, and correlate with various clinical parameters of MM, such as ISS stage, β-2-microglobulin and creatinine levels." (PMID 29695106, 2018). "Our present study aimed at elucidating the role played by genetic variability in BSG and SLC16A1 (MCT1) in myeloma cells." (PMID 29695106, 2018). "This pattern of BSG and MCT1 overexpression was also observed earlier in multiple myeloma." (PMID 35054026, 2022). "Additionally, overexpressed BSG and MCT1 were demonstrated to be involved in energy metabolism in MM by the means of supporting the export of toxic lactate anions in myeloma cells." (PMID 29695106, 2018).
psoriasis (13 papers, 2017 to 2025). An autoimmune condition characterized by red, well-delineated plaques with silvery scales that are usually on the extensor surfaces and scalp. "We and others showed that rs8259 T allele was associated with decreased level of BSG expression and sBSG, as well as decreased risk of psoriasis and ACS." (PMID 28230811, 2017). "Notably, a miR-492 binding-site polymorphism (rs8259 A > T) in BSG 3′UTR was associated with decreased BSG mRNA and protein levels in peripheral blood mononuclear cells (PBMCs) or plasma from healthy subjects and patients with psoriasis and acute coronary syndrome (ACS)." (PMID 28230811, 2017).
squamous cell carcinoma (13 papers, 2010 to 2023). A carcinoma arising from squamous epithelial cells. "MCT1 and MCT4 were expressed in all squamous cell carcinoma type cases, and BSG was expressed in 60% of the cases." (PMID 25894929, 2015).
head and neck squamous cell carcinoma (12 papers, 2013 to 2024). A squamous cell carcinoma that arises from any of the following anatomic sites: lip and oral cavity, nasal cavity, paranasal sinuses, pharynx, larynx, and salivary glands. "CD147/basigin (BSG) is highly upregulated in many types of cancer, our previous study has found that CD147/BSG is highly expressed in head and neck squamous cell carcinoma (HNSCC) stem cells, but its role in HNSCC and the underlying mechanism is still unknown." (PMID 30421493, 2019).
SARS-CoV infection (12 papers, 2020 to 2024). "Besides this, BSG is also involved in HIV and SARS-CoV infection." (PMID 38034398, 2023).